KLK4 (kallikrein related peptidase 4)
Diseases named in the same sentence as KLK4 in open-access papers (continued):
Sharing a sentence is not in itself a finding about the gene and the disease.
asthma (1 paper, 2023). "The only GWAS of T2-low adult asthma (n = 1350) revealed a genome-wide significant association (rs117639512, OR for A allele = 0.33, p-value = 2.75 × 10−8) in the intergenic region between kallikrein-related peptidase 4 (KLK4) and kallikrein-related peptidase 5 (KLK5) genes." (PMID 37761964, 2023).
bladder cancer (1 paper, 2020). "The PCR signals of six genes (KLK3, TMPRSS2, KLK4, IGF1R, VEGF, and MYC) were successfully amplified in bladder cancer cell lines." (PMID 32781788, 2020).
chromophobe renal cell carcinoma (1 paper, 2018). Chromophobe renal cell carcinoma is a rare subtype of renal cell carcinoma, originating from the intercalating cells of the collecting ducts and macroscopically manifesting as a well-circumscribed, highly lobulated, solid tumor that is usually diagnosed at an early stage. "Chromophobe renal cell carcinoma also had 4 up-regulated KLKs with excellent diagnostic power (KLK2: 0.990, KLK3: 0.974, KLK4: 0.989, KLK15: 0.97)." (PMID 29707153, 2018). "Our analysis differed and found that KLK1, KLK2, KLK3, KLK4 and KLK15 are highly upregulated in chromophobe renal cell carcinoma." (PMID 29707153, 2018). "Thyroid carcinoma had three KLKs (KLK2: 0.943, KLK4: 0.914, KLK15: 0.905) that had AUC values above 0.90 threshold and KLK7 had an AUC of 0.910 in Chromophobe renal cell carcinoma." (PMID 29707153, 2018). "Chromophobe renal cell carcinoma had increased expression of the following KLKs: KLK1 (32-fold), KLK2 (12-fold), KLK3 (69-fold), KLK4 (234-fold), KLK15 (132-fold), whereas decreased expression of KLK5 (5-fold), KLK6 (13-fold), and KLK7 (26-fold)." (PMID 29707153, 2018). "We identified four viable cancer biomarkers (KLK2, KLK3, KLK4 and KLK15) for chromophobe renal cell carcinoma with almost perfect sensitivity and specificity (AUC values: 0.97–0.99)." (PMID 29707153, 2018).
cutaneous melanoma (1 paper, 2017). A primary melanoma arising from atypical melanocytes in the skin. "In concordance with our findings, a previous gene expression study revealed that KLK7, KLK4, and KLK11 expression is correlated with metastatic dissemination and associated with overall survival of patients with primary cutaneous melanoma." (PMID 28636767, 2017).
dementia (1 paper, 2023). Loss of intellectual abilities interfering with an individual's social and occupational functions. "Interestingly, six proteins (NEFL, WNT9A, IL17D, IGFBP2, KLK4, and PGF) were repeatedly selected in both diagnostic models that classified dementia from both cognitively normal controls and MCI." (PMID 37175824, 2023). "Interestingly, in our study, KLK4 and LYN were identified as among the best discriminative plasma proteins for dementia in the MUVR model." (PMID 37175824, 2023). "Notably, NEFL, WNT9A, IL17D, IGFBP2, KLK4, and PGF proteins were included in both models that differentiated dementia from either cognitively normal controls or MCI." (PMID 37175824, 2023).
diabetes (1 paper, 2022). "The exact effect of diabetes on MMP-20 and KLK4 is still unreported, however, our assumption in this regard is based on the literature published by Bartlett JD." (PMID 35327689, 2022).
esophageal tumors (1 paper, 2021). "KLK4 expression was significantly increased in esophageal tumors and cells compared with controls." (PMID 34561425, 2021).
glioma (1 paper, 2022). A benign or malignant brain and spinal cord tumor that arises from glial cells (astrocytes, oligodendrocytes, ependymal cells). "These genes include HMGA1 in glioma, AKT1 in glioma, PTC, GC, and HCC, HEMGN in PTC, APLN and MMP19 in GC, WNT1 in CRC, NUPR1 in CRC and OSCC, LY6E and CTSB in CHOL, KLK4 and PLXNB2 in OC, and HDAC4 and STAT3 in SaOS." (PMID 36175921, 2022). "These miR-637-targeted genes include HMGA1, CDK6, and WNT7A in glioma, HEMGN in PTC, APLN in GC, USP21 in HCC, LY6E and CTSB in CHOL, NUPR1 in OSCC and MM, HDAC4 in SaOS, ABL1 in CML, KLK4 in OC, PLXNB2 in OC, AKT1 in TNBC, PTC, and HCC, AKT3 in TNBC, and RING1 in CCa." (PMID 36175921, 2022).
head and neck squamous cell carcinoma (1 paper, 2014). A squamous cell carcinoma that arises from any of the following anatomic sites: lip and oral cavity, nasal cavity, paranasal sinuses, pharynx, larynx, and salivary glands. "Correlative studies have already provided evidence that five other protein members of KLK family (KLK4, KLK5, KLK7, KLK8, and KLK10) were abundantly expressed in head and neck squamous cell carcinoma, showing diagnostic value." (PMID 24669031, 2014).
laryngeal carcinoma (1 paper, 2015). Carcinoma that arises from the laryngeal epithelium. "Both studies reported a remarkable down-regulation of either KLK4 or KLK11 transcript levels in laryngeal cancer as compared to their non-malignant counterparts." (PMID 25990935, 2015).
laryngeal squamous cell carcinoma (1 paper, 2019). A squamous cell carcinoma that arises from the larynx. "In contrast, in laryngeal squamous cell carcinoma, KLK4 mRNA was proposed to be a favorable biomarker for prognosis." (PMID 30811511, 2019).
melanoma (1 paper, 2017). A malignant, usually aggressive tumor composed of atypical, neoplastic melanocytes. "Also other KLKs – KLK4, 8, and 10 – were found to be present in 30%, 13%, and 39% of melanoma cell lines, respectively (for a summary of the expression pattern of all analyzed KLKs)." (PMID 28636767, 2017).
metastatic tumors (1 paper, 2020). "Additionally, the KLK4 protease has been suggested as a potential regulator of the interaction between PCa cells and the microenvironment of metastatic tumors." (PMID 33255452, 2020). "However, additional work is required to determine the precise function of KLK4 during PCa tumorigenesis in both early and late stage/metastatic disease." (PMID 33255452, 2020).
non-small cell lung carcinoma (1 paper, 2021). A group of at least three distinct histological types of lung cancer, including non-small cell squamous cell carcinoma, adenocarcinoma, and large cell carcinoma. "Initially, LINC00858 was identified as a ceRNA impacting miR-422a to control the expression of kallikrein-related peptidase 4, and its high expression was found to be closely correlated to tumor progression of non-small cell lung carcinomas." (PMID 34760693, 2021).
nonsmall cell lung cancer (1 paper, 2021). "KLK4 is also reported to contribute to nonsmall cell lung cancer progression." (PMID 34561425, 2021).
prostate (1 paper, 2025). "Indeed, KLK14 presence was previously identified as a part of the prostate‐cancer‐related protease network, where secreted KLK14 and KLK4 are recruited to membrane protrusions decorated with cell surface‐bound hepsin and TMPRSS2." (PMID 40621923, 2025).
prostatic intraepithelial neoplasia (1 paper, 2017). "KLK4 is highly expressed in prostate epithelial cells of premalignant (prostatic intraepithelial neoplasia) and malignant lesions compared to normal prostate epithelia, especially at the peristromal interface." (PMID 28510269, 2017). "In prostatic intraepithelial neoplasia (PIN) lesions, KLK4 staining was strong and predominantly localized to the cytoplasm of the secretory cells of prostate glands, and the basal cells of low‐ and high‐grade PIN lesions (LGPIN, HGPIN, closed arrows)." (PMID 28510269, 2017).
Renal clear cell carcinoma (1 paper, 2018). "Renal clear cell carcinoma had six KLKs in which increased expression was associated with overall survival (KLK2: HR = 1.69; KLK4: HR = 1.63; KLK8: HR = 1.71; KLK10: HR = 2.12; KLK11: HR = 1.76; and KLK14: HR = 1.86)." (PMID 29707153, 2018).
thyroid cancer (1 paper, 2018). "In addition, thyroid carcinoma displayed significant downregulation of KLK2 (13-fold) and KLK4 (9-fold)." (PMID 29707153, 2018). "Also, our ROC analysis indicates that KLK2 and KLK4 can be used as novel biomarkers for thyroid cancer, since previous studies have not reported any kallikreins as biomarkers for thyroid cancer." (PMID 29707153, 2018).
uterine corpus endometrial carcinoma (1 paper, 2018). A endometrial carcinoma (disease) that involves the body of uterus. "Furthermore, uterine corpus endometrial carcinoma displayed significant overexpression of KLK12 (3-fold) and downregulation of KLK1 (5-fold), KLK2 (4-fold) and KLK4 (6-fold)." (PMID 29707153, 2018).
cancer (36 papers, 2010 to 2026). A tumor composed of atypical neoplastic, often pleomorphic cells that invade other tissues. "KLK4 (Kallikrein-related peptidase 4) is considered to be an oncogene associated with various types of cancers." (PMID 39061962, 2024). "It was also observed that fibroblasts adjacent to the HGPIN foci are induced to acquire the cancer-associated fibroblasts (CAFs) phenotype via secreted factors by prostate epithelial cells, such as kallikrein-related peptidase-4 (KLK4)." (PMID 36139572, 2022). "Since the discovery of the KLK4 gene it has been demonstrated that multiple KLK4 transcripts variants are produced in cancer cells." (PMID 33255452, 2020). "KLK4 has been implicated in promoting PCa progression by stimulation of tumor growth and metastasis through induction of cancer‐associated fibroblast phenotypes in prostate stromal cells, epithelial to mesenchymal transition‐like characteristics, and activation of matrix metalloproteinase‐1 (MMP‐1)." (PMID 41531507, 2026). "One member of this family, KLK4, has been implicated in cancer development and metastasis." (PMID 27767076, 2016). "We previously reported that KLK4 induces cancer-associated fibroblast features in prostate-derived stromal cells, induces epithelial to mesenchymal transition (EMT)-like characteristics, and activates matrix metalloproteinase-1 (MMP-1), which, together, could impact tumor growth and metastasis." (PMID 33255452, 2020). "Other KLKs have emerged as key players in PCa pathogenesis, particularly KLK2, KLK4, and KLK14, which are implicated in cancer progression through protease activity, AR modulation, and interaction with extracellular matrix components." (PMID 41531507, 2026). "Published reports indicate that KLK4 facilitates the spread of cancer cells via basement membrane and connective tissue degradation." (PMID 32630820, 2020). "KLK4 exerts autocrine effects on cancer cells and paracrine effects on surrounding normal cells, in turn regulating key signalling pathways." (PMID 28510269, 2017). "With the emerging role of tissue kallikreins in cancer, KLK4 expression has been profiled in several cancer tissues e.g. prostate, ovary, endometrium and colon." (PMID 25888189, 2015). "KLK4-MCAs formed larger cancer cell foci in mesothelial cell monolayers than those formed by vector and native SKOV-3 cells, suggesting KLK4-MCAs are highly invasive in the peritoneal microenvironment." (PMID 23451143, 2013). "Like the KLK7 spheroids the KLK4-MCAs were able to invade into mesothelial cell monolayers and produced larger cancer cell foci than those formed by vector and native SKOV-3 cells." (PMID 23451143, 2013). "KLK4 and KLK5 were reported to be associated with poor outcome in grade 1 and 2 tumors, indicating their association with aggressive forms of cancer." (PMID 23319948, 2012). "Understanding the regulation of KLK4 catalytic mechanisms may inspire us to devise potential clinical strategies to intervene in the progression of cancer as well." (PMID 36814474, 2023). "Identifying the factors that regulate KLK4 activity is important for enamel biology and enamel tissue regeneration and may also shed light on cancer biology." (PMID 36814474, 2023). "Therefore, we used TagetScan, miRDB, and miRcode platforms to search the potential targets of miR-765 and found KLK4 as a candidate, which has a critical effect on cancer progression." (PMID 34561425, 2021). "Increasing studies have suggested that KLK4 plays a tumor-supporting role in cancer." (PMID 34561425, 2021). "KLK4 immunoreactivity was present in the cytoplasm of Gleason grade 3 + 3, 3 + 4, 4 + 5 cancers." (PMID 28510269, 2017). "Hence, KLK4 is an important mediator of the uPA/uPAR axis which is known to have an important role in cancer invasion." (PMID 24043563, 2014). "In addition, we and others have reported that high tumor levels of KLK4 and KLK7 were associated with chemoresistance in patients with this cancer." (PMID 24043563, 2014).
cancer (continued). "For example, at a biochemical level, active KLK4 cleaves pro-uPA generating active single chain uPA which is induced by ascites in EOC cells and is associated with chemoresistance and poor prognosis in women with this cancer." (PMID 23451143, 2013). "However, to date, these functional studies of KLK4 in cancer have been limited to in vitro models." (PMID 33255452, 2020). "Furthermore, KLK4–7 regulate gene expression of other cancer-related factors: simultaneous overexpression of these four KLKs lead, e.g., to a distinct up-regulation of moesin and keratin 19 mRNA and protein expression, while keratin 7 is strongly down-regulated." (PMID 31307411, 2019). "Interestingly, KLK4 is also overexpressed in cancer of the endometrium, ovary, and the prostate." (PMID 24294176, 2013). "We identified distinct genes including KLK4, FN1, PBOV1, TPM2, and FLNA which are known to be involved in PCa pathways along with IGF1, TPD52, and SRSF1 that are involved in different cancer pathways." (PMID 37218885, 2023). "Our data show strong evidence that proves that increasing the expression level of miR-378 in cells by EPA induces the PGC-1β gene, which possibly affects KLK2, KLK4, KLK6, and KLK14 gene expression in cancer cells." (PMID 35681793, 2022). "Other signature genes, including PTN, KLK4, RGMA and PIGR, have also been reported to be involved in cancer progression." (PMID 29642861, 2018). "Evidence also showed for a novel double-paracrine mechanism whereby cancer epithelium produces KLK4 to activate PAR-1 in the surrounding stroma, which in-turn releases cytokines (IL-6) that stimulate cancer cells to proliferate and increase production of KLKs." (PMID 29291033, 2017). "KLK4 staining in PIN, Gleason 3 and 4 cancers, was higher than in BPH (P < 0.001, one‐way ANOVA), whereas KLK4 expression in normal prostate was lower than in BPH (P < 0.023)." (PMID 28510269, 2017). "In cancer tissues, pro-HGFA is likely activated by thrombin and/or human kallikrein 1-related peptidase (KLK)-4 and KLK-5." (PMID 25268161, 2014). "The human kallikrein 1-related peptidases KLK4 and KLK5 are also potent activators of pro-HGFA in the cancer cell microenvironment." (PMID 25268161, 2014). "In addition, KLK4 is also overexpressed in PCa and involved in processes critical for establishment of the TME and cancer progression." (PMID 28510269, 2017). "In this report, we demonstrated that KLK4 can induce a CAF‐like phenotype, which is essential for cancer progression, in normal prostate stromal cells, and may be a key contributor to CAF differentiation in PCa." (PMID 28510269, 2017). "This demonstrated that EPA could significantly induce PCa cell death by down-regulating the KLK2, KLK4, KLK6, and KLK14 genes in PCa cells, then triggering apoptosis in the cancer cells; however, a similar mechanism did not affect the normal cells." (PMID 35681793, 2022).
tumor (32 papers, 2008 to 2023). "As reported by Obiezu and co-workers, a significant association was observed between elevated KLK4 mRNA levels and clinical stage as well as tumor grade." (PMID 30811511, 2019). "KLK4 is key regulator on the proliferation of several tumor cell lines, and is associated with higher risk of NSCLC as determined by univariate analysis and confirmed by multivariate analysis." (PMID 28177876, 2017). "In conclusion, these reports show that the role of KLK4 proteins in PCa is very context- and, possibly, isoform-dependent and that proteins encoded by KLK4 could perform either pro- and/or anti-tumor functions during PCa progression." (PMID 33255452, 2020). "However, KLK4 could still fulfill important regulatory roles via activation of signaling molecules or modulation of tumor-associated pathways." (PMID 30811511, 2019). "In prostatic cancer (PC), TAGLN (tumor suppressor) and HLA had higher expression in the periphery, whereas NUPR1 and KLK4 etc. were expressed higher in the tumor core." (PMID 36313703, 2022). "Proteinase-activated receptor-1 (PAR1), triggered by thrombin and other serine proteinases such as tissue kallikrein-4 (KLK4), is a key driver of inflammation, tumor invasiveness and tumor metastasis." (PMID 34373558, 2021). "Contrary to KLK4, the Ki67 expression, representing tumor cell proliferation rate, was as expected, positively correlated to the disease stage." (PMID 34884832, 2021). "KLK4 expression was reported to be strongly positively correlated with clinical stage and tumor grade." (PMID 33150763, 2020). "The bone surface area to volume ratio was the highest for mandibles harboring PC3-PSMA/Vec tumors, as compared to those harboring PC3-PSMA/KLK4 tumors, or non-tumor controls." (PMID 33255452, 2020). "Since KLK4 tumor production inhibited the growth of orthotopically implanted tumors, we next investigated if similar effects were also observed in a bone-metastastic model whereby tumor cells were injected intracardiac in mice for arterial blood dissemination." (PMID 33255452, 2020). "The KLK4 tumor inhibitory effects was confirmed by weekly in vivo optical imaging, with the bioluminescence of KLK4-secreting tumors observed lower than control tumors over the three weeks." (PMID 33255452, 2020). "That notwithstanding, our work demonstrates that the classical form of KLK4 (secreted serine protease) exerts an anti-tumor role in both an orthotopic and experimental metastasis in vivo model using the aggressive PC3 PCa bone metastatic-derived cell line." (PMID 33255452, 2020). "In line with the proposed signaling functions, we recently demonstrated that KLK4, in combination with KLK5, 6, and 7, regulates gene expression of other tumor-relevant genes such as MSN (encoding moesin), KRT7 and KRT19 (encoding keratins 7 and 19)." (PMID 30811511, 2019). "Compared with the OE-LINC01314 group, tumor weight was found to be reduced in the OE-LINC01314 + si-KLK4 group but elevated in the OE-LINC01314 + LiCl group (all p < 0.05)." (PMID 31007611, 2019). "Taken together, we propose that epithelial‐derived KLK4 promotes tumour progression by actively promoting CAF differentiation in the prostate stromal microenvironment." (PMID 28510269, 2017). "These KLK4–7 expressing OV-MZ-6 cells increased tumor growth in an animal model compared to OV-MZ-6 cells expressing the single KLK4, KLK5, KLK6 or KLK7, or vector controls." (PMID 24043563, 2014). "As KLK4 and KLK7 are up-regulated in EOC cells and tumor tissue samples, with high levels associated with poor outcome in women with this disease [87, 102???], we over-expressed these peptidases in SKOV3 EOC cells to determine their function." (PMID 24043563, 2014). "Kaplan-Maier survival analysis showed that the patients with high tumor KLK4 had significantly shorter progression free (PFS, χ2 = 8.3, P = 0.004) and overall survival time (χ2 = 4.9, P = 0.03) than those with low KLK4." (PMID 23451143, 2013).